DMD (dystrophin)
Diseases named in the same sentence as DMD in open-access papers (continued):
Sharing a sentence is not in itself a finding about the gene and the disease.
Sepsis (3 papers, 2013 to 2022). Sepsis is defined as life-threatening organ dysfunction caused by a dysregulated host response to infection. "Herein, we have demonstrated, for the first time, that calpain-1 inhibition reduces the loss of essential cardiac cytoskeletal (dystrophin and β-dystroglycan) and contractile (sarcomeric actin and myosin) proteins during sepsis." (PMID 27880847, 2016). "Cultured neonatal mouse cardiomyocytes subjected to serum obtained from mice with severe sepsis presented strikingly higher [Ca2+]i and calpain-1 levels associated with decreased expression of dystrophin and disruption and derangement of F-actin filaments and cytoplasmic bleb formation." (PMID 23935889, 2013). "Cultured neonatal mice cardiomyocytes subjected to serum obtained from mice with severe sepsis presented striking increment of [Ca2+]i and calpain-1 levels associated with decreased expression of dystrophin and disruption and derangement of F-actin filaments and cytoplasmic bleb formation." (PMID 23935889, 2013). "In another clinical trial (NCT03199469) of AAV-mediated X-linked myotube myopathy, two children died of sepsis, and potential high-dose AAV toxicity was also observed in some subjects enrolled in the DMD gene therapy trials." (PMID 36012442, 2022). "In the present study, we demonstrate that severe sepsis induced a significant reduction in cardiac structural proteins dystrophin and β-dystroglycan examined 24 hours after induction of sepsis employing the CLP model." (PMID 27880847, 2016). "The amount of dystrophin was strikingly reduced in septic hearts at 24 hours after sepsis induction as compared with the mean value in hearts from sham-operated mice, corroborating previous data from our laboratory." (PMID 23935889, 2013). "In addition, sepsis reduced the expression of structural proteins dystrophin and β-dystroglycan as well as the contractile proteins actin and myosin." (PMID 27880847, 2016). "Recently, using an experimental sepsis model based of cecal ligation and puncture (CLP), our research group demonstrated a marked reduction in cardiac dystrophin, an important protein involved in assembling and maintaining of the link between cytoskeletal actin and the extracellular matrix." (PMID 27880847, 2016).
adenoma (2 papers, 2018 to 2019). A neoplasm arising from the epithelium. "Genes NCKAP1L and DMD, identified in the main cluster of the cancer network, were identified as mutated in a considerable percentage of the cases of adenomas, adenocarcinomas and squamous cell neoplasms whose primary site was bronchus and lung, and which were registered at the GDC portal by TCGA." (PMID 31766738, 2019). "In the DMD alone group, the CEA and Tg levels of adenoma-bearing rats were higher than that of the tumor-free rats (p < 0.05) as well as the rats with hyperplasia only (p < 0.05)." (PMID 29495605, 2018). "The levels of Ki67 and PCNA in the DMD alone group were higher than that of the resveratrol-treated groups and their levels in the hyperplasia and adenoma tissues were stronger than the surrounding noncancerous tissues." (PMID 29495605, 2018).
Amyloid (2 papers, 2024 to 2025). "Amyloid plaque burden was found to be significantly associated (P < 4.39 × 10−4) with methylation changes in FRMPD4, ARHGAP6 (in the FRMPD4 locus), and DMD." (PMID 39633006, 2025). "Three conditions had more than 1 gene or RNA therapy available: DMD (n = 4 drugs), SMA (n = 3 drugs), and polyneuropathy of hereditary transthyretin-mediated amyloidosis (n = 3 drugs)." (PMID 38770270, 2024).
anxiety disorder (2 papers, 2012 to 2023). A category of psychiatric disorders which are characterized by anxious feelings or fear often accompanied by physical symptoms associated with anxiety. "Previous studies imply that the abnormality of certain genes is associated with anxiety disorders, such as CRHR1, FKBP5, CREB, Egr-1, Glo1, Gsr, AC8, CaMKIV, dystrophin, HTTLPR and COMT Met158." (PMID 22681774, 2012). "We propose that a lack of full-length Dp427 dystrophin leads to a dysfunctional fear system which predisposes individuals with DMD to develop anxiety disorders." (PMID 35136951, 2023).
astrocytomas (2 papers, 2017 to 2022). "To confirm whether dystrophin protein is expressed in LGG tissue, and in which cell types, we conducted a pilot immunohistochemistry study on a cohort of 24 LGG cases (18 astrocytoma, one oligodendroglioma and five NOS) using a C-terminal dystrophin antibody which detects all dystrophin proteins." (PMID 35217778, 2022).
atherosclerosis (2 papers, 2015 to 2017). A disease characterized by the build-up of fatty material and calcium deposition in the arterial wall resulting in partial or complete occlusion of the arterial lumen. "The present study is the first to demonstrate a role for dystrophin in atherosclerosis and unexpectedly shows that this primarily involves immune cells." (PMID 26345322, 2015). "To investigate the role of dystrophin in intimal recruitment of smooth muscle cells (SMCs) that maintains plaque stability in atherosclerosis we applied a shear stress-modifying cast around the carotid artery of apolipoprotein E (ApoE)-null mice with and without the mdx mutation." (PMID 26345322, 2015).
behavioral disorders (2 papers, 2021 to 2022). "The prevalence rates of comorbid diagnoses in neurodevelopmental and behavioral disorders differed between the DMD and NF1 group." (PMID 36215287, 2022).
bladder cancer (2 papers, 2021 to 2022). "The seed gene DMD seems more related to survival, while the transgelin gene TAGLN is closely connected to oncogenic transformation and, consequently, prognosis in bladder cancer patients." (PMID 36175974, 2022).
Breast Invasive Carcinoma (2 papers, 2017 to 2023). "In other studies, mutations in the DMD gene were associated with poor overall survival of patients of two out of 11 analyzed tumors, namely uterine corpus endometrioid carcinoma and breast invasive carcinoma." (PMID 36900171, 2023). "Likewise, the presence of a mutation in DMD shortened the overall survival of patients with Uterine Corpus Endometrioid Carcinoma and Breast Invasive Carcinoma." (PMID 27391342, 2017).
Cachexia (2 papers, 2010 to 2021). Severe weight loss, wasting of muscle, loss of appetite, and general debility related to a chronic disease. "Dystrophin overexpression in mice counteracted cancer-induced muscle loss and atrogene expression, indicating DGC disruption as a major switch of cachexia development." (PMID 33401549, 2021). "Alterations in the dystrophin complex that anchors muscle fibers to the basement membrane have been reported to occur in C26-induced cachexia; this may explain the blurred appearance of laminin, one of the main components of the basement membrane." (PMID 20615237, 2010). "Conversely, reduced dystrophin protein levels, but not transcript ones, represent an early event in cachexia development, since they occurred before the reduction in mean fiber diameter." (PMID 33401549, 2021).
channelopathies (2 papers, 2020 to 2022). "In subject 2.1 and 2.2 focused single gene analysis comprised NGS panel for genes associated with channelopathies, Long QT syndrome, DMD, LPIN1, and RYR1 were negative." (PMID 31339582, 2020).
dementia (2 papers, 2018 to 2022). Loss of intellectual abilities interfering with an individual's social and occupational functions. "Expression levels of these elements predict dementia status and p-tau levels in the aging human brain and dystrophin-deficient astrocytes have altered astrocyte function and altered AQP4 levels." (PMID 35473943, 2022). "In contrast, DMD expression was significantly reduced in the HIP of subjects with dementia (t = 2.632, padj = 0.013)." (PMID 30120299, 2018). "Like the established DAC genes AQP4, DTNA, DAG1 and DMD, expression of several endfoot candidate genes differed between dementia-free and subjects with dementia." (PMID 30120299, 2018).
developmental disabilities (2 papers, 2023). "Patients with seizures (n = 19) and with intellectual/developmental disabilities (n = 39) commonly had in‐frame deletions in the middle or the second half (exon 45–55 range) of the coding region of the dystrophin rod domain (respectively)." (PMID 37882106, 2023).
gastric cancer (2 papers, 2015 to 2023). A primary or metastatic malignant neoplasm involving the stomach. "For example, the DMD gene in Xp21.1 was identified as a driver gene in gastric cancer, and our result suggests that it may also contribute to EA development." (PMID 26374103, 2015). "In addition to DMD and HUWE1, we also found an association of DNAH family mutations with TMB, which was in accordance with findings that somatic mutation of the DNAH gene family was associated with higher TMB and better chemotherapy treatment response in gastric cancer patients." (PMID 37741340, 2023).
glioma (2 papers, 2022 to 2025). A benign or malignant brain and spinal cord tumor that arises from glial cells (astrocytes, oligodendrocytes, ependymal cells). "Thus, considering our own data implicating ECM-linked dystrophin proteins in low-grade glioma, an area of future investigation could be whether higher levels of these structural protein(s) more effectively support the LGG tumour microenvironment." (PMID 35217778, 2022). "Our data from two independent cohorts suggests that overall DMD expression is significantly associated with survival outcomes in only the less invasive, IDH mutant, gliomas indicating a likely role for DMD in the early stages of gliomagenesis." (PMID 35217778, 2022). "In our own preliminary study to determine the effect of high versus low DMD gene expression on survival outcomes across all cancers, we found that low-grade glioma (LGG) returned one of the highest hazard ratios." (PMID 35217778, 2022). "Overall, our data identifies DMD expression as an independent prognostic marker for LGG and highlights a potentially important role for DMD gene product(s) in the progression of low-grade glioma." (PMID 35217778, 2022). "The Dp71 isoforms have not been studied in low grade glioma before and studies on DMD in cancer have not fully considered the complexity of the gene and the roles its individual gene products may play." (PMID 35217778, 2022).
hemophilia (2 papers, 2015 to 2018). Hemophilia is a genetic disorder characterized by spontaneous hemorrhage or prolonged bleeding due to factor VIII or IX deficiency. "While minimally impacting the normal transcriptome, Upf3b-ASO treatment significantly stabilizes the PTC-containing dystrophin mRNA in mdx mice and coagulation factor IX mRNA in a hemophilia mouse model." (PMID 29334995, 2018).
Hyperkalemia (2 papers, 2012 to 2025). An abnormally increased potassium concentration in the blood. "It has been reported that isoflurane anesthesia or stress induced rhabdomyolosis, hyperkalemia and death in dystrophin-deficient cats." (PMID 22691118, 2012).
hyperthyroidism (2 papers, 2023 to 2025). Overactivity of the thyroid gland resulting in overproduction of thyroid hormone and increased metabolic rate. "The corresponding mutated genes set that has common effects on hyperthyroidism in children included IGF1, CACNA1S, MYH7, IL6, TTN, CACNB2, LAMA2, and DMD." (PMID 37876543, 2023).
Immunodeficiency (2 papers, 2015 to 2020). Failure of the immune system to protect the body adequately from infection, due to the absence or insufficiency of some component process or substance. "Rag2-/γ chain-/C5- mice have a more profound immunodeficiency than the mdx nude mouse, while the latter is dystrophin deficient and its muscles exhibit pathological features, such as muscle degeneration and regeneration, accompanied by the infiltration of inflammatory cells." (PMID 25949786, 2015).
infarction (2 papers, 2019 to 2025). A localised pathological necrosis of tissue resulting from obstruction of the blood supply usually by a thrombus, an embolus, or vascular torsion. "Using dystrophin immunohistochemistry for membrane staining, human post-infarction myocardial tissue was assessed." (PMID 31417141, 2019).
Infertility (2 papers, 2017 to 2025). "Although the results suggest the involvement of dystrophin and utrophin during the development of male reproductive organs, the contribution of utrophin in mdx/utrn+/− mouse infertility needs further investigation." (PMID 28785010, 2017).
laminopathies (2 papers, 2015 to 2023). "While a comprehensive functional study of membrane proteins, such as integrins, dystrophin complex proteins, and other specialized complexes such as the desmosome, is beyond the scope of this work, the role of membrane adhesion in laminopathies is intriguing and prompt future investigations." (PMID 26323789, 2015).
memory impairment (2 papers, 2020 to 2021). "Moreover, a low level of Dmd is associated with changes in brain function, such as increased attention deficit, memory impairment, and increased risk of seizure, suggesting that dystrophin plays a role in brain function." (PMID 34630032, 2021).
Myalgia (2 papers, 2012 to 2023). "“In frame” deletions of variable extent, mostly in the rod domain of the dystrophin gene, have been reported before in individuals with no or with very mild symptoms, such as elevated serum CK or myalgia." (PMID 22707356, 2012).
neuropathies (2 papers, 2022 to 2023). "GDF15 was significantly elevated in CMT in comparison to the non-neuropathy disease controls GNE myopathy and BMD/DMD." (PMID 35148379, 2022).
olfactory neuroblastoma (2 papers, 2018 to 2021). An olfactory neuroblastoma arising in the paranasal sinus. "In line with DMD deletions in STS, in olfactory neuroblastoma these are concentrated in the 5’ end of the gene and all but one are predicted to preserve Dp71 expression." (PMID 33188621, 2021).
prostate carcinoma (2 papers, 2021 to 2025). A carcinoma that arises from epithelial cells of the prostate gland. "Rare damaging variants in CHEK2 (OR = 1.69 [1.41–2.01], P = 2.69 × 10−8) and rare synonymous variants in DMD (OR = 0.50 [0.36–0.67], P = 8.6 × 10−7) were associated with prostate cancer risk at the suggestive significance threshold." (PMID 39971927, 2025). "At the gene level, we also identified TET2 and DMD to be associated with the risk of prostate cancer." (PMID 39971927, 2025). "In case of prostate cancer, the expression of DMD decreased further when the cells became metastatic." (PMID 33188621, 2021).
renal cell carcinoma (2 papers, 2019 to 2021). "Overall, with the exception of renal cell carcinoma in which DMD is upregulated, there is a trend for DMD downregulation across numerous carcinomas." (PMID 33188621, 2021). "Copy number losses were also identified in DLG2 (8% WGS samples), SETD2 (4% WGS), and DMD (29% WGS), genes previously associated with other human cancers such as OS, renal cell carcinoma and myogenic sarcomas." (PMID 31341965, 2019).
retinal ischemia (2 papers, 2020 to 2022). A ischemic disease that involves the retina. "DMD expression in the human retina is required for normal function and its products have been reported related to regulate retinal function and vascular morphology in response to age and retinal ischemia." (PMID 32337810, 2020).
soft tissue tumors (2 papers, 2011 to 2021). "In recent studies, dystrophin (Dp427) has been implicated in tumorigenesis of soft tissue tumors and therefore coined a “tumor suppressor” and a likely anti-metastatic agent." (PMID 34575126, 2021). "During the last two decades we have observed the spontaneous occurrence of soft tissue tumors arising from various skeletal limb and trunk muscles in our dystrophin-deficient C57BL/10 mdx-mouse cohort." (PMID 21533183, 2011).
status epilepticus (2 papers, 2016 to 2023). Status epilepticus is defined as a continuous seizure lasting more than 30 min, or two or more seizures without full recovery of consciousness between any of them. "This was highlighted by the study of Kim and colleagues in which a reduction of AQP4 expression in brain tissue during the post-status epilepticus period was demonstrated, which in turn is associated with down-regulation of dystrophin and alpha-syntrophin complex." (PMID 37569297, 2023).
thalassemia (2 papers, 2007 to 2024). An inherited blood disorder characterized by a decreased synthesis of one of the polypeptide chains that form hemoglobin. "In order to modify exon 27 splicing, we used splice-site ASOs, which have previously been used to modify splicing in the dystrophin gene and to correct the aberrant alternative splicing in the ß-thalassemia mutation IVS2-654." (PMID 17233885, 2007). "In addition, one carrier couple was heterozygous for α-thalassemia, and the female partner was also a carrier of DMD." (PMID 38297315, 2024).
Thrombocytopenia (2 papers, 2020 to 2022). A reduction in the number of circulating thrombocytes. "Clinical trials with dystrophin exon 51 skipping 2OMePS antisense oligonucleotides (AONs) have reported improvements in DMD however, they were also accompanied by some side effects e.g. proteinuria and moderate thrombocytopenia, that hampered progress." (PMID 33298994, 2020).
X-linked AHC (2 papers, 2022 to 2023). "Xp21 deletion usually contains DAX1 (resulting in X-linked AHC), GK (resulting in glycerol kinase deficiency), and DMD deletion (resulting in Duchenne muscular dystrophy)." (PMID 37237297, 2023). "This suggests that most of the contiguous gene deletions in patients with DAX1-related X-linked AHC contain DAX1, GK, and DMD deletions." (PMID 37237297, 2023).
acute myeloid leukemia (1 paper, 2023). Acute myeloid leukemia (AML) is a group of neoplasms arising from precursor cells committed to the myeloid cell-line differentiation. "The hierarchical clustering analysis revealed that the blood malignancies acute myeloid leukemia (LAML) and diffuse large B-cell lymphoma (DLBC) had a unique pattern of DMD transcripts, to the point that these two malignancies were classified as a separate cluster." (PMID 36900171, 2023).
anemia (1 paper, 2012). A reduction in the number of red blood cells, the amount of hemoglobin, and/or the volume of packed red blood cells. "The nine infants without samples either had left prior to receiving the fingerstick or already had the fingerstick for the anemia test at a previous visit and no extra blood had been collected for DMD screening." (PMID 22866242, 2012).
aspiration pneumonia (1 paper, 2024). "The supraglottic aspiration and accumulation of residue seen in patients with dysphagia may lead to silent aspiration, which is presumed to be a common cause of aspiration pneumonia and sudden death among non-ambulatory patients with DMD." (PMID 38630313, 2024).
Atrophy (1 paper, 2016). Any weakening or degeneration, especially through lack of use. "Initial studies on muscle from phase-2 participants showed SS muscle atrophy was accompanied by a decrease in the frequency of slow-type fibers expressing MyHC1 protein, a lower vascular density, and increases in atrogin-1, dystrophin, and VEGF proteins compared to the ipsilateral control muscle." (PMID 27668864, 2016).
autoimmune disease (1 paper, 2025). A disorder resulting from loss of function or tissue destruction of an organ or multiple organs, arising from humoral or cellular immune responses of the individual to their own tissue constituents. "There are currently several clinical trials underway using C3 inhibitors (e.g., AMY-101 and APL-2) and TLR 7/8/9 antagonists (e.g., IMO-8400) for various inflammatory and autoimmune diseases, indicating that these drugs may be readily incorporated into DMD gene therapy clinical trials." (PMID 40098958, 2025).
blood pressure (1 paper, 2023). "Mutations in dystrophin in VSMCs lead to significantly increased expression of KCNQ5 and RYR2, potentially resulting in low blood pressure in DMD patients." (PMID 37569835, 2023).